TET2 (tet methylcytosine dioxygenase 2)
Diseases named in the same sentence as TET2 in open-access papers (continued):
Sharing a sentence is not in itself a finding about the gene and the disease.
tumor (continued). "Furthermore, we showed that VC increases chemokine gene CXCL9/-10/-11 expression in a TET2-dependent manner, leading to type I T cell attraction to tumor sites and to enhanced checkpoint inhibitor responses." (PMID 39388288, 2024). "In addition, DNA demethylase, TET2, modulates anti-tumor immunity by elevating cGAS levels in tumor cells." (PMID 39606248, 2024). "Additionally, a positive correlation was found between tumor TET2, STAT5A, cGAS expression and intratumoral CD8+ T cell infiltration." (PMID 38177099, 2024). "While TET2 ChIPs at the B2M promoter, its loss only weakly reduces B2M expression in B16 cells and does not reduce B2M tumor expression as measured through flow cytometry, indicating a role for additional actors in promoting B2M gene expression." (PMID 39388288, 2024). "Overall, these results demonstrate that TET2 has tumour suppressive activities." (PMID 37620362, 2023). "TET2 has also been shown to play a key role in tumour progression." (PMID 37667220, 2023). "In addition, TET2 represses tumor cell growth and colony formation by inactivating mTORC1 signaling, providing a new mechanism for TET2-mediated suppression of tumor growth." (PMID 37550284, 2023). "Among them, DNMT3b, DNMT1, ALYREF, TET2, NSUN2 and NSUN5 mutations imply that m5C may act abnormally in the tumour." (PMID 37408139, 2023). "As amino acids are vital for mTORC1 activation, we thus examined the effect of TET2 KO on the levels of 20 amino acids by mass spectrometry and found that levels of several amino acids including arginine are altered in both TET2 KO tumor cells and mouse livers." (PMID 37550284, 2023). "In this study, we demonstrated a tumour suppressor role of TET2 in LUAD." (PMID 37667220, 2023). "To confirm this finding, we performed sgRNA-mediated knockout of TET2 in tumor cells." (PMID 37550284, 2023). "This study reveals a tumour suppressor role of TET2 in LUAD." (PMID 37667220, 2023). "Treatment of CAR T cells with BET inhibitor JQ1 promoted the expansion of less differentiated TSCM and TCM, downregulated PD-1 and TET2 exhaustion marker expression, improved persistence and effector function, and augmented T-cell mediated anti-tumor effect in leukemia models." (PMID 37153607, 2023). "These neoplasms feature a characteristic and similar, but not identical, mutational landscape with mutations in epigenetic modifiers (TET2, DNMT3A, IDH2), RHOA, and T-cell receptor signaling genes." (PMID 36793612, 2023). "Thus, systemic knockout of Tet2 in mice resulted in accelerated tumor growth and was able to impede the anti-PD-1 antibody treatment response." (PMID 37488178, 2023). "TET2 activity is inhibited as tumor growth proceeds, leading to urea cycle activation and arginine production, which in turn activates mTORC1 signaling to enable cell growth, and then proliferation, resulting in the eventual tumor growth." (PMID 37550284, 2023). "Therefore, the activation of TET2 by EMT/WNT/β-catenin pathways is a kind of “side effect” or brake that impairs these key events in a feedback manner during tumour progression." (PMID 37620362, 2023). "Moreover, IHC staining showed increased protein levels of TET2, cGAS, STING and TBK1 in TET2-overexpressing tumours, in which the protein levels of STING and TBK1 were clearly decreased by RU.521 treatment." (PMID 37667220, 2023). "The primary nodal presentation with tumor mainly involving lymph nodes, T-cell origin, lack of nasal involvement, and presence of mutations in TET2 and DNMT3A supports the diagnosis of primary nodal-EBV-TNKL." (PMID 37646869, 2023). "Besides tumor suppressors, inactivation of Tet2 also promoted antitumor activity by enhancing the function of tumor infiltrating lymphocytes." (PMID 36672677, 2023). "Previous studies have shown that tumor suppressor TET2 is the substrate of AMPK." (PMID 35755313, 2022). "CXXC4 and TET2 at 4q24 were equally potential targets for tumor suppression." (PMID 35677048, 2022).
tumor (continued). "Somatic mutations of TET2 occur in about 10% of DLBCL and display a tumor suppressor role." (PMID 35237302, 2022). "The mechanisms by which the overexpression of TET2 influences tumour progression and patient survival may involve the altered regulation of a subset of downstream genes rather than an overall shift in the genome-wide epigenetic state." (PMID 34905094, 2022). "Notably, during tumor growth, TET2 expression was found increased in myeloid-derived suppressor cells and tumor-associated macrophages and preserved immunosuppressive gene expression levels." (PMID 36685517, 2022). "Additionally, loss of TET2 significantly enhanced immune response to CAR T cell therapy and suppressed tumor growth." (PMID 35237302, 2022). "Importantly, repression of miR-10-5p enhances TET2 and 5hmC levels in GSCs and blocks tumor-initiation capacity of GSCs and prolongs survival in orthotopic GBM xenograft models." (PMID 35136034, 2022). "Similarly, using hepatoma as well as breast cancer cell lines, a faster tumor growth in TET2 knockout mice was found due to an IL-6-mediated expansion of MDSCs and a consequently reduced T cell infiltration." (PMID 35663987, 2022). "Moreover, TET2-KO 786-O and A498 cells showed similar tumor growth in the nude mouse model compared to the parental TET2-WT cells." (PMID 35173532, 2022). "Furthermore, vitamin C injection conferred significantly more benefits to mice bearing TET2-WT tumors with slower tumor growth than mice with TET2-KO tumors as an adjuvant for anti-PD-L1 immunotherapy." (PMID 35173532, 2022). "More exhaustive studies are required to determine the exact role of TET2 in tumor development—whether it initiates oncogenesis or acts as a result of tumor development." (PMID 35223782, 2022). "TET2 is considered as a tumor suppressor for its effect on the DNA 5-hydroxymethylome." (PMID 35659740, 2022). "AMPK phosphorylates TET2 at serine 99, thus stabilizing tumor suppressor." (PMID 35755313, 2022). "The versatile functions of TETs may explain why changes in protein expression of TET1 and TET2 are more significant than changes in 5hmC in all the tumor specimens." (PMID 33716151, 2021). "In addition, the level of TET2 in tumor tissues formed by HCC-LM3 cells was significantly inhibited by alcohol exposure in vivo." (PMID 34019487, 2021). "Alcohol exposure decreased TET2 level not only in adjacent tissues but also in tumor tissues." (PMID 34019487, 2021). "Most m5C regulators showed tumor-promoting effects, except for TET2 and NSUN7." (PMID 34957065, 2021). "We also found evidence of tumor suppressor effects, such as negative enrichment for genes down regulated in Kmt2d or Tet2 deficient GCs." (PMID 34621263, 2021). "In addition to its role in demethylation, TET2 appears to act as a tumor suppressor that is involved in the control of balancing survival, growth and differentiation in normal hematopoiesis." (PMID 34039392, 2021). "DNA methylation studies of CpGs in the TET2 upstream promotor region across both NHL tumour-derived and control PBMC samples showed consistently low levels of methylation, and a similar trend was observed in the methylation of genomic DNA in the NHL case-control cohort." (PMID 34899857, 2021). "Besides, suppressing hsa_circRNA_101996/TET2 or overexpressing miR-143 inhibits tumor growth in vivo." (PMID 34659556, 2021). "Recent studies have shown that TET2 could act as a critical player in the regulation of immune homeostasis and anti-tumor immunity." (PMID 34064441, 2021). "Several studies on mouse models proved that TET2 acts as a tumor suppressor as well." (PMID 34947882, 2021). "The role of TET2 as a tumor suppressor is not limited to myeloid derived malignancies." (PMID 36618446, 2021). "PI3K inhibitors efficiently inhibited TET2-/-RHOA G17V tumor proliferation." (PMID 32637355, 2020).
tumor (continued). "To provide further support for the function of TET2-PKM interaction on regulating NPC progress, we subcutaneously injected wild type CNE1 cells (as control), or TET2-knockout (TET2-cas9) cells in nude mice and found that tumor volume increased in TET2-cas9 group, compared with control group." (PMID 32774157, 2020). "The effects of TET2 on NPC progression were evaluated using xenograft tumor model in vivo." (PMID 32774157, 2020). "In addition, TET2 is a DNA methylcytosine dioxygenase that is closely related to tumor resistance and tumor metastasis." (PMID 33041670, 2020). "The abundance of TET2 was negatively connected with the level of miR-660-5p in tumor tissues." (PMID 33146288, 2020). "More importantly, we identified that HDAC4 positively regulates TET2 expression, and HDAC4 knockout significantly enhanced colony forming capacity of murine MDS cells, indicating that HDAC4 serves as a tumor-suppressor in the context of high-risk MDS or normal karyotype AML." (PMID 32726753, 2020). "Moreover, using xenograft tumor model, we found that TET2 knockout promoted NPC progression and decreased survival rate." (PMID 32774157, 2020). "Collectively, these data establish TET2 as a tumor suppressor of B-cell lymphomas." (PMID 33520997, 2020). "Furthermore, tumor sections from the nude mouse model were immunohistochemically stained for TET2, PTEN, and p-AKT." (PMID 33097695, 2020). "However, administration with the inhibitor of PKM, shikonin, decreased the tumor volume of TET2-cas9 group, and increased the survival rate." (PMID 32774157, 2020). "To determine whether reconstitution of TET2 expression in human T-ALL cells affects tumor cell proliferation and viability, we retrovirally introduced full-length TET2 cDNA into CCRF-CEM cells." (PMID 31266538, 2019). "RP11-704M14.1, SFMBT2-4:1, IRAIN, TET2 function as tumor suppressors in AML." (PMID 31681586, 2019). "In contrast to TET1, our results show that TET2 acts as a tumor suppressor in T-ALL." (PMID 31266538, 2019). "Indeed, we found that TET1 KD or ectopic expression of TET2 decreased cell proliferation in T-ALL and was associated with genome-wide changes in 5mC and 5hmC, suggesting a tumor promoting function of TET1, and a tumor suppressing role for TET2." (PMID 31266538, 2019). "Intriguingly, out of seven key TET2-governed genes identified from our model exhibiting differential methylation in normal versus tumor samples in the TCGA at TET2-KO DMS-proximal probes, only one—ASB2—showed significantly decreased, rather than increased, methylation levels in cancer." (PMID 30917865, 2019). "Therefore, TET2 can safeguard the genome mutagenicity and function as a tumor suppressor in hematopoiesis." (PMID 31527484, 2019). "Furthermore, we also found that the expression of STAT5 and TET2 were increased in CD4+ T cells from tumor tissues, and the massive STAT5 binds more TET2 to the FOXP3-TSDR and upregulates FOXP3 expression." (PMID 30013992, 2018). "Although TET2 mutations have not been reported in human ICC, TET2 is believed to harbor tumor suppressive function linked to IDH1/2, which are among the commonly mutated oncogenes in ICC." (PMID 30158952, 2018). "The results showed that STAT5 could combine with TET2 to form a complex, and more complexes were found in tumor tissues compared with normal tissues." (PMID 30013992, 2018). "TET2 promoter methylation has previously been observed in low-grade diffuse gliomas lacking IDH1/2 mutations and provides a third mechanism to cause loss in maintenance of 5hmC levels in the tumour." (PMID 29263824, 2017). "Furthermore, the roles of TET proteins in the regulation of cancer progression are probably different in that TET1 is primarily involved in tumor initiation while TET2 and TET3 are primarily involved in cancer metastasis." (PMID 27852070, 2017).
tumor (continued). "Furthermore, this 5-hmc defect was more pronounced in tumor T cells from acute patients than from chronic ones and correlated with reduced expression of TET2 protein." (PMID 28881727, 2017). "Furthermore, the discovery that WT1 cooperates with TET2 to upregulate MEG3 expression places TET2-WT1-MEG3 signaling axis as a central tumor suppressive pathway in AML, therefore emphasizing the potentials of this axis in AML diagnosis and therapy." (PMID 28400619, 2017). "Moreover, transcriptional inactivation of SALL3 was associated with aberrant methylation of other tumor-related genes and TET1, TET2, and DNMT3A levels in HNSCC." (PMID 28616099, 2017). "Notably, the overexpression of TET2 significantly reduced tumor formation as indicated by reduced tumor volume and longer survival time of the mice." (PMID 27852070, 2017). "Indeed, TET2 protein expression was barely detectable in tumor T cells from the acute patient while a significant TET2 signal was observed for the chronic patient." (PMID 28881727, 2017). "Moreover, comparison between tumor T cells from the acute or chronic patient revealed that the TET2 staining mirrored the 5-hmc signals." (PMID 28881727, 2017). "Both TET1 and TET2 are implicated in cancer: TET1 is an MLL partner in cases of acute myeloid and lymphoid leukemias and has been reported to function as an oncogene in MLL-rearranged leukemias as well as a tumor suppressor in other contexts [reviewed in Ref." (PMID 28408905, 2017). "It would be interesting to inquire whether TET2 suppresses tumor formation in these solid tumors in WT1-dependent or -independent pathways." (PMID 26861406, 2016). "TET2 and TET3 expression was also significantly decreased in tumor tissues compared with paired non-tumor tissues (TET2, P < 0.0001; TET3, P = 0.009), and the decrease in 5-hmC was significantly associated with the downregulation of TET2 expression (r = 0.405, P = 0.004)." (PMID 27050164, 2016). "This might also explain why loss of function of TET2 contributes to myeloid malignancies such as MDS and AML due to silencing of tumour suppressor genes via aberrant promoter methylation." (PMID 25276435, 2014). "miR-22-induced inhibition of the ten-eleven-translocation gene 2 (TET2) tumor suppressor increased the methylation of TET2 target genes, such as Aim2, Hal, Igbt2, and Sp140, and resulted in positive effects on hematopoietic stem cell self-renewal and transformation." (PMID 24427168, 2014). "Only RUNX1 and TET2 may be inactivated in the two-hit fashion that corresponds to "classical" tumor suppressors." (PMID 20678218, 2010). "Furthermore, the integration of TET2 status into predictive models can enhance the stratification of patients, thereby facilitating individualized treatment plans that consider the unique genetic landscape of each tumour." (PMID 41169875, 2025). "Consistent with previous studies, TET2 and DNMT3A mutations were observed in non‐tumor cells including myeloid or B‐cells, suggesting early founding mutation in a progenitor cell in a subset of cases, but other mutations like IDH2, RHOA, and CD28 appeared to be tumor‐specific." (PMID 40510016, 2025). "Global genomic reduction in 5hmC, potentially mediated by loss of TET2 function, has been reported as an independent adverse prognostic marker for OS in a cohort of NSCLC patients (n = 208), with low 5hmC levels significantly associated with large tumor size and lymph node metastasis." (PMID 40116537, 2025). "Notably, hypomethylating agents (HMAs) may be able to target not only tumor cells but also TET2-CH-derived non-tumor cells." (PMID 40164718, 2025). "Furthermore, TET2 may facilitate tumor-induced immune response activation and immune infiltration in CRC, thus exerting an anticancer effect." (PMID 38356721, 2024). "Importantly, in Tet2 or Stat5a deficiency cells-derived tumors, the combination of VC and anti-PD-L1 had no obvious changes in tumor burdens as compared to single VC or anti-PD-L1 therapy." (PMID 38177099, 2024).
tumor (continued). "One antigen presentation process was identified in cluster 9 in the TET2-KO tumor treated with VC among those top 20 enriched pathways, consistent with previous data showing that loss of TET2 expression in the tumor does not block the effect of VC on the dendritic cell/macrophage cluster." (PMID 39388288, 2024). "According to the Centrality and Density, prognosis, immunotherapy, and tumor microenvironment have emerged as popular and extensively studied topics since 2021, differing from earlier research where some hotspots such as tet2 and transcription RNA have gradually been replaced." (PMID 39726589, 2024). "Lastly, we determined the functional significance of the TET2-mTORC1 axis in tumor growth and found that TET2 KO significantly strengthens capacity for cell proliferation and colony formation of tumor cells, as well as proliferation of mouse primary liver cells." (PMID 37550284, 2023). "Besides, overexpression of ASL or ASS1 promotes cell proliferation, indicating that TET2-urea cycle-mTORC1 axis may play an important role in tumor growth." (PMID 37550284, 2023). "Although TET-2 mutations are considered secondary events in nMTCL-TFH-phenotype, different studies demonstrate an association of TET-2 and RhoA G17V mutations in these neoplasms, suggesting a biological cooperation between both mutations to promote AITL development." (PMID 37182145, 2023). "In addition, the combination of IM12 and Vc may also suppress the growth of tumours with low TET2 expression, since Vc has a high ability to activate TET proteins." (PMID 37620362, 2023). "Functionally, we find that loss-of-function mutations in Tet2, the most common premalignant alteration in BPDCN, confer resistance to UV-induced cell death in plasmacytoid, but not conventional, dendritic cells, suggesting a context-dependent tumour-suppressive role for TET2." (PMID 37286599, 2023). "Thus, Tet2 is a critical tumor suppressor in hematopoietic tissue." (PMID 36203205, 2022). "Mechanistically, we showed that transcriptional factor Bcl6 co-opted the demethylase Tet2 and the deacetylase SIRT1 to confer the epigenetic imprinting and mitochondrial metabolic traits to SMMs, bolstering the stability and longevity of trained immunity in tumor-associated macrophages (TAMs)." (PMID 36542153, 2022). "In addition, the correlation between TET2 expression and the tumor microenvironment was quantitatively assessed using the R package “ESTIMATE”, and the correlation coefficients of TET2 expression and ESTIMATE, stromal, and immune scores were evaluated separately." (PMID 35223782, 2022). "We then assessed whether TET2 depletion affects cell or tumor growth." (PMID 35173532, 2022). "Moreover, TET2 controlled chemoresistant slow-cycling cancer cell survival and tumor recurrence." (PMID 32209730, 2020). "Furthermore, there is rare study about the role of TET2 methylation in tumor prognosis." (PMID 32066746, 2020). "As reduced TET2 levels are correlated with advanced PCa and decreased survival, we assessed the ability of changes in expression of our 27 TET2-target candidate genes to discriminate based on pathological stage, Gleason score (GS), and recurrence in the TCGA dataset (n = 423 tumor samples)." (PMID 30917865, 2019). "Similarly, TET2 has been reported to be a tumor suppressor in B-cell lymphomagenesis." (PMID 31266538, 2019). "Moreover, they suggest that a distinct 5-hmc/TET2 pattern may distinguish tumor T cells from acute patients from those from chronic patients." (PMID 28881727, 2017). "Therefore, these small molecules may also inhibit other important enzymes that require alpha-ketoglutarate as a co-factor for their enzymatic activities, such as TET2 (ten-eleven translocation 2) hydroxylase, which has a tumor suppressor function." (PMID 24146981, 2013).